PTX3 (pentraxin 3)
Diseases named in the same sentence as PTX3 in open-access papers (continued):
Sharing a sentence is not in itself a finding about the gene and the disease.
tumor (continued). "Again, PTX3 overexpression conferred an increased proliferative rate and capacity to growth under anchorage independent conditions in vitro, as well as higher tumor growth capacity to E0771 PTX3 cells when implanted orthotopically into syngeneic C57BL/6 female mice." (PMID 37749607, 2023). "Importantly, we demonstrate that the pro-tumor activity of PTX3 is exerted via the activation of the TLR4 pathway which is known to play a relevant role in TNBC aggressiveness." (PMID 37749607, 2023). "In addition, KD-mediated immunity regulates tissue injury and PTX3 plays a crucial role in tumor remodeling and repair." (PMID 37941784, 2023). "Moreover, nonmutant fibroblasts have the potential to increase the proliferation of mutant desmoid tumor cells by secreting soluble factors that include PTX3, CCL2, and CXCL12." (PMID 37377751, 2023). "Similarly, PTX3 levels in cervical cancers and gliomas appear to correlate with tumor grade and severity in vitro and in patients." (PMID 37749607, 2023). "In this scenario, we evaluated the PTX3 expression and analyzed the potential role of complement system activation on tumor site and immune microenvironment modulation, stratifying samples in tumors with high (MUC1H) versus tumors with low MUC1 expression (MUC1L)." (PMID 36902242, 2023). "Altogether, our findings suggest that the direct targeting of PTX3 or TLR4 may represent a promising novel therapeutic approach for the treatment of TNBC as well as other tumor types where TLR4 signaling activation strictly depends on PTX3 expression." (PMID 37749607, 2023). "Interestingly, doxorubicin treatment enhances doxorubicin-induced tumor metastasis in mouse xenograft models by priming the premetastatic niche in a PTX3-dependent manner, and promotes the secretion of TNBC-EVs enriched in PTX3." (PMID 36835116, 2023). "In addition, the expression level of PTX3 was positively correlated with tumor malignancy degree, sustained the migration and proliferation of tumor cells, and dysregulates mitogenic signaling pathways, encouraging tumor escape from immune responses." (PMID 37063077, 2023). "Indeed, tumor and/or host PTX3 overexpression can inhibit FGF-driven epithelial-to-mesenchymal transition (EMT) and tumor/metastatic burden in melanoma models and hampers cancer growth in models of fibrosarcoma, prostate and bladder cancer." (PMID 37749607, 2023). "In this frame, limited experimental evidence suggests that PTX3 may be endowed with a tumor-promoting activity in TNBC." (PMID 37749607, 2023). "Other studies support the hypothesis that PTX3 exerts a pro-tumorigenic effect promoting macrophage infiltration and tumor cell migration and invasion." (PMID 37025408, 2023). "Compared to LGG, HGG showed increased PTX3 mRNA levels in patients’ tumor samples." (PMID 36153549, 2022). "Studies have shown that PTX3 may hinder the presentation of apoptotic cell‐derived antigens, which supports that PTX3 may inhibit the anti‐tumor immune process in the tumor microenvironment." (PMID 35855654, 2022). "In the meantime, we determined that tumor patients may benefit from immunotherapy as PTX3 correlated with immunotherapy predictors." (PMID 36139597, 2022). "Importantly, we linked PTX3 to immunotherapy, synthetically underscoring its importance in human cancers and providing the prospect of PTX3 and immunotherapy for tumor patients." (PMID 36139597, 2022). "FGFRL1-KD, via increasing PTX3, could thus strongly affect cellular functions, tumor growth, and vascularization." (PMID 35053442, 2022). "In the present study, we provide evidence that PARPi could impair the VM formation to inhibit the tumor progression via its action to inhibit the NF-kB activity, which subsequently leads to a decrease of PTX3." (PMID 36555812, 2022). "Angiogenesis is crucial for the tumor growth and studies have demonstrated that PTX3 could be an inducer or an inhibitor of angiogenesis." (PMID 36555812, 2022).
tumor (continued). "Importantly, PTX3 levels in the blood of experimental mice bearing allograft E0771‐Luc2 tumours were correlated with the expression of CEBPD and were positively associated with growth and metastasis." (PMID 35090088, 2022). "PTX3 may promote the stemness of tumor cells through Hedgehog and Hippo-YAP signaling pathways, so as to expedite tumor growth and malignant progression." (PMID 35982954, 2022). "Our finding was supported by the previous study that PTX3 may play dual (pro‐tumor and anti‐tumor) roles in cancer, depending on tumor type, cellular source, and tumor microenvironment." (PMID 35855654, 2022). "PTX3 could recruit and combine with Factor H to inhibit tumor‐related inflammation by regulating complement‐dependent tumor‐related inflammation, thus acting as an exogenous tumor suppressor to inhibit tumor‐related inflammation." (PMID 35855654, 2022). "PTX3 might act as the treatment and intervention targets, and might provide new immunotherapy strategies for tumor patients." (PMID 36139597, 2022). "PTX-3 expression could also be targeted by anti-tumor treatment and could facilitate further development of drugs." (PMID 36499628, 2022). "In other tumor contexts, C1q deposition through PTX-3 activation could lead to angiogenesis inhibition and reduced inflammatory responses." (PMID 36499628, 2022). "In this study, PTX3 was further found to mediate the migration and inflammation‐resolving‐polarization of microglia in the tumor microenvironment of GBM, in which microglia had enhanced ability in migration and increased expression of CD163 under the stimulation of PTX3." (PMID 35855654, 2022). "Besides, CD68 and CD163 were more co‐expressed in tumor tissues with high PTX3 expression than in tumor tissues with low PTX3 expression." (PMID 35855654, 2022). "Consequently, the roles of PTX-3 in cancer depend on the type of the tumor and microenvironment, as different signaling pathways are regulated through PTX-3." (PMID 36499628, 2022). "PTX-3 has both pro- and anti-tumor functions, thus dual functions in oncogenesis." (PMID 36499628, 2022). "The intra‐tumor distribution of PTX3 in GBM tissues was evaluated." (PMID 35855654, 2022). "This work explores, for the first time, the anti-angiogenic role of PTX3 produced by MM cells demonstrating that the inducible expression of PTX3 is able to impair MM neovascularization, the onset of a proficient BM vascular niche and, ultimately, to impair tumor growth and dissemination." (PMID 34066669, 2021). "PTX3 exhibits antitumoralactivity when released from the tumor stroma." (PMID 34048179, 2021). "In addition, using microarray analysis, we also identified the overexpression of LOX and PTX3 in KARS and PIK3CA mutant cell lines compared to the HMOsisEC10 cells, which was associated with the aggressive behavior of the benign tumor." (PMID 34202354, 2021). "Most cell types, including tumor cells, are able to produce PTX3." (PMID 33917524, 2021). "PTX3 overexpression in PC and other tumor types was considered as an unfavorable prognostic factor." (PMID 34830209, 2021). "However, the expression levels of PTX3 in LUAD were significantly negatively correlated with tumor purity and positively correlated with B cells, CD8+ T cells, CD4+ T cells, neutrophils, and dendritic cells." (PMID 34745947, 2021). "Since PTX3 may affect many types of tumor cells, it is essential to clarify the biological role of PTX3 in tumor development." (PMID 34149932, 2021). "Our observations are in line with previous evidences, which indicate that PTX3 could modulate the tumor microenvironment and could be a local or systemic marker of cancer-related inflammation." (PMID 32345771, 2020). "PTX3 has been revealed to be an extrinsic oncosuppressor in preclinical models and certain tumors through regulating complement-driven macrophage-mediated tumor progression and tuning cancer-related inflammation." (PMID 33219288, 2020).
tumor (continued). "Notably, research reported that inhibited PTX3 expression significantly decreased tumor size on GBM xenografts." (PMID 32984316, 2020). "Besides, PTX3 binds to fibroblast growth factor-8b receptor (FGF8b) and inhibits tumor cell proliferation in steroid hormone-regulated tumors." (PMID 33013829, 2020). "PTX3 modulates tumor cell adhesion and metastasis by interacting with the FGFR system." (PMID 33013829, 2020). "Tumor-infiltrating macrophages and neutrophils also carry the potential to suppress the detrimental effects of complement activation through IL-1ß-induced expression of pentraxin 3 (PTX3)." (PMID 32733461, 2020). "In addition, PTX3 has an involvement in various phases of tumor development, comprising tumorigenesis, angiogenesis, metastasis, and tumor immunomodulation." (PMID 32194791, 2020). "Recently, PTX3 has been proved its role in tumor progression." (PMID 32984316, 2020). "PTX3 not only participates in immune system activation but also affects tumor progression." (PMID 33013829, 2020). "The neuronal pentraxins and PTX3 possess specific unique receptors that mediates tumor progression." (PMID 33013829, 2020). "Recent studies have shown how PTX3 can influence the pathogenesis of different cancer types, but plays an ambivalent role, i.e. acting as a tumor suppressor or pro-oncogenetic factor in relation to the neoplastic type and the tumor microenvironment." (PMID 32345771, 2020). "Then, we performed in vitro experiments to prove PTX3 affects tumor cells viability and autophagy." (PMID 32984316, 2020). "However, the roles of PTX3 in various cancers have been seemingly controversial, with reports showing both tumor-suppressing and promoting effects of PTX3 in tumor stemness, growth and metastasis." (PMID 32427938, 2020). "Notably, PTX3 can interact with the fibroblast growth factor-2/fibroblast growth factor receptor system to promote tumor progression." (PMID 32984316, 2020). "In addition, we established that higher manifestation level of PTX3 apparently lessened the manifestation of E-cadherin as well as N-cadherin in the tumor tissues." (PMID 32194791, 2020). "Furthermore, JUN is identified as potential transcription factor involves in pentraxin 3 mediated tumor cells autophagy." (PMID 32984316, 2020). "The double-sided effect of PTX3 recommends that its function in cancer may be precisely reliant on the type of cancer, cell origin and tumor microenvironment." (PMID 32194791, 2020). "PTX3 may exert a significant impact on tumor growth and angiogenesis in different tumor types, and has been reported to play a relevant role in the regulation and recruitment of innate immune cells." (PMID 31533326, 2019). "Thus, genetic studies in mice and epigenetic studies in humans demonstrate that PTX3 behaves as an extrinsic oncosuppressor gene by acting at the level of complement-mediated, macrophage-sustained, tumor promoting inflammation." (PMID 31019517, 2019). "These contradictory results suggest that PTX3 may have a dual role in cancer, likely depending on the type of cancer, or on the cells producing it, in particular tumor cells or infiltrating macrophages, fibroblasts and endothelial cells." (PMID 31019517, 2019). "Notably, miR-224 targets pentraxin 3 (Ptx3), which is a potent tumor suppressor for ESCC, and stimulates ovarian E2 release." (PMID 31164411, 2019). "BC cell lines, representative of different tumor grades, and transgenic/carcinogen-induced models were used to demonstrate in vitro and in vivo that PTX3 production by tumor cells decreases along the progression from low-grade to high-grade advanced muscle invasive forms (MIBC)." (PMID 31480336, 2019). "Indeed, PTX3-overexpressing B16-LS9 tumor grafts showed a reduced rate of growth in syngeneic mice and a reduced metastatic activity when injected in the blood stream of zebrafish embryos." (PMID 31487962, 2019).
tumor (continued). "Given the role of FGF2 in the maintenance of cancer stem-like cells, the loss of stem-like traits in PTX3 overexpressing BC cells might be the result of the FGF trap action of PTX3, with a possible significant impact on different tumor features." (PMID 31480336, 2019). "In addition, B16-LS9 cells showed a reduced tumor growth and liver metastatic activity when grafted in PTX3-overexpressing transgenic mice." (PMID 31487962, 2019). "Depletion of PTX3 and inhibition of NF-κB decreased tumor cell migration and invasion." (PMID 30740360, 2019). "In vivo, when grafted into immunocompromised mice, PTX3 downregulation resulted in increased tumor burden of RT4-shPTX3 lesions when compared to control and wild-type tumors, accompanied by an increased proliferation index as assessed by immunostaining for phospho-histone H3-positive (pHH3+) cells." (PMID 31480336, 2019). "As such PTX3 does seem to have a direct effect on tumor cell growth." (PMID 30619374, 2018). "In conclusion, FGF2/PTX3 interaction may exert a deep impact on the angiogenesis process during inflammation and tumor growth." (PMID 30349543, 2018). "Moreover, PTX3 has been proposed as an extrinsic oncosuppressor, able to affect tumor-promoting inflammation mediated by complement and macrophages." (PMID 30443492, 2018). "Furthermore, we found that oleate-induced PTX3 expression and tumor invasion were inhibited by DN-IκB and an NF-κB inhibitor." (PMID 28489600, 2017). "Therefore, the ability of oleate-induced PTX3 to promote the interaction between the tumor cells and endothelial cells was examined." (PMID 28489600, 2017). "Several observations point to a safeguarding role of PTX3 against cardiovascular disease (CD) and tumor, acting through a functional/efficient tuning of the inflammation process and representing an extreme attempt of the body to limit an excessive inflammatory response." (PMID 28536575, 2017). "In addition, both the depletion of PTX3 and the inhibition of NF-κB significantly inhibited oleate-induced tumor cell migration and invasion." (PMID 28489600, 2017). "Whether the roles of tumor-derived and extrinsically derived PTX3 in the regulation of metastasis and tumor growth, respectively, are associated with the glycosylation of proteins remains to be clarified." (PMID 28489600, 2017). "The association of high PTX3 levels and JAK2V617F homozygous status with haematological evolution and all-cause mortality suggests that inflammation in the tumour microenvironment might contribute to the genetic instability and disease progression of MPNs." (PMID 28228104, 2017). "However, the transient knockdown of PTX3 in tumor cells dramatically reduced the formation of pulmonary nodules induced by oleate." (PMID 28489600, 2017). "Oleate also activated integrin β1 in HNSCC (our unpublished data), suggesting that the activation of integrin signaling might participate in PTX3-regulated tumor/endothelial interactions." (PMID 28489600, 2017). "Furthermore, the depletion of PTX3 blocked the oleate-primed metastatic seeding of tumor cells in the lungs." (PMID 28489600, 2017). "Although PTX3 is a representative marker of cancer-related inflammation, whether PTX3 acts as a tumor promoter or tumor suppressor remains controversial." (PMID 27458153, 2016). "Additionally, the clinical and biological function of PTX3 showed that it has the potential to be a prognostic biomarker with a tumor promoting activity factor in bone metastatic breast cancer." (PMID 27377307, 2016). "We further studied PTX3 expression in various malignant tumor cells treated with EGF." (PMID 25797258, 2015). "Our findings not only describe the biological significance of PTX3 in tumorigenesis but also suggest that PTX3 may be a key pro-tumorigenic player in the tumor microenvironment." (PMID 26124179, 2015). "Importantly, tail-vein injection animal model revealed that depletion of PTX3 significantly blocked EGF-primed tumor cell metastatic seeding of the lungs." (PMID 25797258, 2015).
tumor (continued). "Sarcomas growing in Ptx3−/− host showed a much higher macrophage and neutrophil infiltrate, and higher levels of CCL2, CXCL2, TNFα, IL-6, IL-1β, and VEGF, suggesting an exacerbated tumor-associated inflammatory response." (PMID 26075183, 2015). "Previous observations had shown that the soluble pattern recognition receptor PTX3 binds FGF8b and inhibits the angiogenic and tumorigenic activity of androgen-regulated tumor cells in which testosterone activates a FGF8b-dependent autocrine/paracrine loop of stimulation." (PMID 25912421, 2015). "To test the possibility that the metastatic process enhanced by EGF-induced PTX3 also occurs by regulating the interaction between tumor and endothelial cells, we examined whether EGF induces the binding of HNSCC cells to HMEC-1 endothelial cells." (PMID 25797258, 2015). "In this context, identification of the PTX3 gene as a key player in cancer may also help to better rationalize the role of inflammation in tumor growth." (PMID 26075183, 2015). "Finally, PTX3 mRNA was increasingly up-regulated from peritumor to tumor tissue in comparison to expression levels in host tissue." (PMID 21489226, 2011). "Furthermore, a strong association between elevated PTX3 expression and higher serum alpha fetoprotein (AFP) levels, larger tumor size, and more advanced tumor stages suggests that PTX3 could serve as a prognostic biomarker for HCC." (PMID 41479916, 2025). "Therefore, understanding the specific role of PTX3 in macrophage polarization and function may provide insights into therapeutic strategies aimed at reprogramming macrophages to adopt more anti-tumor phenotypes." (PMID 40656950, 2025). "In addition to promoting EMT, PTX3 may enhance other aggressive features of tumor cells, such as stemness." (PMID 39594709, 2024). "Moreover, PTX3 shows oncogenic dual function abilities, both pro- and anti-tumor functions." (PMID 38730589, 2024). "Furthermore, it has been shown that PTX3 may play a role as an extrinsic tumor-suppressor gene by controlling complement-dependent and macrophage-associated tumor-promoting inflammation." (PMID 38136377, 2023). "For instance, high levels of PTX3 have been reported in all subtypes of human soft tissue liposarcoma as well as in pancreatic carcinoma cells and in advanced gastric cancer tissues where it promotes the migratory potential of tumor cells and macrophages recruitment." (PMID 37749607, 2023). "PTX3 may exert anti-tumor or pro-tumor effects depending on tumor type and context." (PMID 37749607, 2023). "Furthermore, studies have shown that PTX3 might be involved in tumor biology and might exert distinct functions in different cancers." (PMID 36139597, 2022). "Furthermore, PTX3 expression was correlated with tumor stage in KICH, KIRC, LUAD, and THCA." (PMID 36139597, 2022). "In addition, high PTX3 levels have been observed in tumor endothelial cells." (PMID 36555812, 2022). "Moreover, PTX3 acts as a tumor suppressor by blocking the action of pre‐tumor growth factors." (PMID 35855654, 2022). "Moreover, PTX3 promotes cellular proliferation, confers resistance to apoptosis by altering cell cycle signalling, thereby promoting cancer cell invasion and migration, and tumour escape from immunosurveillance." (PMID 34572075, 2021). "However, the function of PTX3 in stemness and tumor-associated macrophages (TAMs) polarization in GC has not yet been revealed." (PMID 34149932, 2021). "Thus, the detected upregulation of PTX3 and C4 may contribute to the clearance of apoptotic cancer cells and tumor shrinkage after five treatments." (PMID 33917524, 2021). "Therefore, PTX3 may be assumed to play a protective role for carcinogenesis in inflammatory tumor microenvironment relying on regulation of complement activation." (PMID 33746606, 2021).